LINC03074 (long independently transcribed non-coding RNA 3074)
Synonyms: LOC127898556; LOC105377488; LOC127898557
Gene: Long non-coding RNA gene on chromosome 4 (151,798,140 to 151,969,381, forward strand). Ensembl gene ENSG00000251249.
Diseases named in the same sentence as LINC03074 in open-access papers:
LINC03074 is named in the same sentence as 3 diseases in open-access papers, as found by Europe PMC text mining. Sharing a sentence is not in itself a finding about the gene and the disease. The quoted sentences say what the papers report.
seminoma (1 paper, 2024). A radiosensitive malignant germ cell tumor found in the testis (especially undescended), and extragonadal sites (anterior mediastinum and pineal gland). "The expression pattern of LINC03074, which was significantly higher in normal tissues than in cancerous tissues of the testes of patients with seminoma, was confirmed via relative quantitative analysis using RT-qPCR (P = 0.00178)." (PMID 39097584, 2024). "We further quantified the expression of LINC03074 in four types of cultured cells derived from seminoma and non-seminoma tissues and found that its expression was significantly higher in TCam-2 seminoma cells." (PMID 39097584, 2024). "The results revealed that LINC03074 was localized to the nucleus and cytoplasm of normal spermatids, whereas it was mainly localized to the nucleus of seminoma cells." (PMID 39097584, 2024). "In this study, we demonstrated that the p73, a target gene of E2F1 related to apoptosis, is involved in the responsiveness of seminoma cells to cisplatin, and its expression is regulated by LINC03074." (PMID 39097584, 2024). "We decided to use TCam-2 cells as a model for seminoma cells in the following experiments, considering that LINC03074 is likely to function in seminomas according to its expression pattern." (PMID 39097584, 2024).
cancer (1 paper, 2024). A tumor composed of atypical neoplastic, often pleomorphic cells that invade other tissues. "In addition, the significance of the differences in LINC03074 levels between carcinoma and normal testis tissues needs to be investigated." (PMID 39097584, 2024).
LINC03074 also shares sentences with these, for which no sentence is quoted: testicular germ cell tumor (1 paper).